PGR (progesterone receptor)
Diseases named in the same sentence as PGR in open-access papers (continued):
Sharing a sentence is not in itself a finding about the gene and the disease.
breast cancer (continued). "According to our study, the expression or lack of expression of Her-2, ER, and PgR does not seem to have a direct effect on the nature of the location of lymphocytes in relation to the breast carcinomas that we examined." (PMID 17892570, 2007). "It completely abolished the mitogenic effect induced by 17β-estradiol in ER+ breast cancer cells, but affected neither ER regulation nor estrogen-induced progesterone receptor expression, as documented in MCF-7 cells." (PMID 16417650, 2006). "A new progesterone receptor-negative, androgen receptor-positive human breast cancer cell line, designated Y-AR, was engineered and characterized." (PMID 16457685, 2005). "So far, the reason for the observed negative relations between the levels of PMN-E and ER and PgR, which we also showed in a larger series of 1143 primary breast cancer patients in which we studied the prognostic value of PMN-E, is not clear." (PMID 12671709, 2003). "Phosphoglycerate mutase, enolase and 2,3-bisphosphoglycerate phosphatase presented greater changes in the oestrogen receptor-negative/progesterone receptor-negative breast carcinomas than in the steroid receptor-positive tumours." (PMID 10638961, 2000). "Since it is known that PGR can synergize with or antagonize ESR to influence downstream biological processes 11, it is important to develop the new type of PGR-specific small molecules for a simple and more effective treatment of HR+ breast cancers without the need of combination treatments." (PMID 41510152, 2026). "Triple-negative breast cancer (TNBC) represents 10-20% of breast cancers and is characterized by the absence of estrogen receptor, progesterone receptor, and human epidermal growth factor receptor 2 expression, leaving cytotoxic chemotherapy as the main systemic treatment." (PMID 41899235, 2026). "Triple-negative breast cancer (TNBC) remains a clinically aggressive subtype of breast cancer, defined by the absence of estrogen receptor, progesterone receptor, and HER2 amplification, and disproportionately affecting younger and racially diverse populations." (PMID 41383624, 2025). "Triple-negative breast cancer (TNBC) accounts for about 15% -20% of all breast cancers and is the deadliest breast cancer subtype characterized by a lack of oestrogen receptor (ER), progesterone receptor (PR) and human epidermal growth factor receptor 2 (HER-2) expression." (PMID 40657248, 2025). "Breast cancer is not a single disease, but a heterogeneous group of malignancies defined by the presence or absence of molecular markers such as estrogen receptor (ER), progesterone receptor (PR), and HER2 amplification." (PMID 40076867, 2025). "Triple-negative breast cancer (TNBC) accounts for approximately 10–20% of all breast cancer cases and is defined by the absence of established hormone receptors, including estrogen receptor (ER), progesterone receptor (PR), and human epidermal growth factor receptor 2 (HER2)." (PMID 41002447, 2025). "Among the different types of breast cancer, they are named according to their respective receptor presence, namely human epidermal growth factor receptor (HER) 2 positive, progesterone receptor (PR) positive, estrogen receptor (ER) positive breast cancer, and triple‐negative breast cancer (TNBC)." (PMID 40600779, 2025). "Triple‐negative breast cancer (TNBC), which is characterised by the absence of oestrogen receptor (ER), progesterone receptor (PR) and human epidermal growth factor receptor 2 (HER2), causes the highest risk of recurrence and the worst prognosis among all breast cancer subtypes." (PMID 40916080, 2025).
breast cancer (continued). "Triple‐negative breast cancer (TNBC) accounts for approximately 15%–20% of all breast cancers and is defined as a lack of the expression of estrogen receptor (ER), progesterone receptor (PgR), and the amplification of the human epidermal growth factor 2 (HER2) receptor." (PMID 41360639, 2025). "Triple-negative breast cancer (TNBC) represents a distinct subtype of breast cancer (BC) characterized by the lack of expression of estrogen receptor (ER) and progesterone receptor (PR), and the absence of human epidermal growth factor receptor 2 (HER2) amplification." (PMID 40342488, 2025). "Hormone receptor (HR)-low/HER2-negative breast cancers (BCs) are more likely to be basal-like BCs, with similar molecular features and gene expression profiles to HR-negative (estrogen receptor <1% or negative and progesterone receptor <1% or negative) BCs." (PMID 38567311, 2024). "Breast cancer is a heterogeneous disease with various histological and molecular features and is divided into three major subtypes depending on the presence or absence of molecular markers: ER or progesterone receptor and HER2." (PMID 39682205, 2024). "Notably, in breast cancer, PRMT1 promotes tumor cell proliferation, tumorigenesis, and metastasis by methylating substrates such as H4, BRCA1, C/EBPα, EZH2, Progesterone Receptor (PR), PHGDH, and SRSF1." (PMID 40018367, 2024). "Triple-negative breast cancer (TNBC) is a category of breast cancer characterized by the absence of estrogen receptor (ER) expression, progesterone receptor (PR) expression, and human epidermal growth factor receptor 2 (HER2) expression, as determined by immunohistochemistry (IHC)." (PMID 38410339, 2024). "Breast cancer is commonly associated with brain metastases, particularly in the case of triple-negative breast cancer (TNBC) defined by the absence of estrogen receptor (ER), progesterone receptor (PR), and human epidermal growth factor 2 (HER2)." (PMID 38762624, 2024). "Three important markers that are generally used to classify breast cancer involve the positive or negative presence of the estrogen receptor (ER), progesterone receptor (PR), and/or the human epidermal growth factor receptor 2 (HER2) protein on the cell surface." (PMID 39057065, 2024). "Importantly, approximately 15% of all breast cancers do not express estrogen receptor (ER), progesterone receptor (PR), or human epidermal growth factor receptor 2 (HER-2); this type is referred to as triple-negative breast cancer (TNBC)." (PMID 39201489, 2024). "Additionally, breast cancer is broadly classified into subtypes according to the presence or absence of hormone receptors (estrogen receptor (ER) and progesterone receptor (PR)) and human epidermal growth factor receptor 2 (HER2)." (PMID 38539518, 2024). "Triple-negative breast cancer (TNBC) is a subtype of breast cancer distinguished by negative expression of estrogen receptor (ER), progesterone receptor (PR), and human epidermal growth factor receptor 2 (HER2) expression, comprising approximately 15–20% of all breast cancer cases." (PMID 38933280, 2024). "TNBC represents a significant clinical challenge in the landscape of breast cancer due to its unique molecular profile characterized by the absence of estrogen receptor (ER), progesterone receptor (PR), and human epidermal growth factor receptor 2 (HER2) expression." (PMID 39369580, 2024). "Triple-negative breast cancer (TNBC) represents a highly aggressive and complex subtype of breast cancer characterized by the absence of three important receptors: the estrogen receptor (ER), the progesterone receptor (PR), and the human epidermal growth factor receptor 2 (HER2)." (PMID 38318597, 2024). "The treatment strategies for breast cancer mainly include immunotherapy that targeting breast cancer-related genes, namely, nonspecific expression of human epidermal growth factor receptor (HER2), estrogen, or progesterone receptor and chemotherapy for triple-negative breast cancers (TNBCs)." (PMID 38318188, 2024).
breast cancer (continued). "Notably, PHGDH knockdown had no impact on the proliferation of estrogen and progesterone receptor-positive breast cancer cells." (PMID 38945960, 2024). "Breast cancer subtypes investigated among the articles found among this review included luminal A, luminal B, human epidermal growth factor receptor 2 (HER2) +/-, estrogen receptor (ER) +/-, progesterone receptor (PR) +/-, and triple negative breast cancer (TNBC)." (PMID 39593069, 2024). "Triple-negative breast cancer (TNBC) is a heterogenous subtype of breast cancer (BC) that is characterized by the lack of estrogen receptor, progesterone receptor expression, along with normal expression levels of human epidermal growth factor receptor 2 (HER2)." (PMID 39594632, 2024). "Nowadays breast cancer clinical treatment selection is based on the immunohistochemical (IHC) determination of four protein biomarkers: Estrogen Receptor 1 (ESR1), Progesterone Receptor (PGR), Human Epidermal Growth Factor Receptor 2 (HER2), and proliferation marker Ki-67." (PMID 39000458, 2024). "Triple negative breast cancer (TNBC) is a type of breast cancer that is negative for oestrogen receptor, progesterone receptor and human epidermal growth factor receptor 2, is highly malignant and aggressive, lacks of corresponding targeted therapy, and has a relatively poor prognosis." (PMID 39054484, 2024). "The same clinicopathological features and prognosis have been reported between single progesterone receptor-positive (sPR-positive) and triple-negative phenotype in early-stage breast cancer, but such similarity has not been studied in metastatic breast cancer (MBC)." (PMID 36910652, 2023). "Breast cancer (BC) is a heterogenous disease classified into four molecular subtypes (Luminal A, Luminal B, HER2 and triple-negative (TNBC)) depending on the expression of the estrogen receptor (ER), the progesterone receptor (PR) and the human epidermal receptor 2 (HER2)." (PMID 37445276, 2023). "To note, our study demonstrated the independent prognostic value of median vessel size when adjusting for age, tumor size, histological grade, HER2 status, progesterone receptor status, and lymph node status in multivariable Cox analysis, not previously shown in the ER + breast cancer subtype." (PMID 37222874, 2023). "Triple‐negative breast cancer (TNBC), defined as breast cancer that is estrogen receptor‐, progesterone receptor‐, and human epidermal growth factor receptor 2‐negative, accounts for 10%–15% of all breast cancers in Japan and is associated with a poor prognosis." (PMID 36916728, 2023). "Of the molecular subtypes of breast cancer, the triple-negative subtype (triple-negative breast cancers [TNBCs]), in which hormone receptors (HRs: estrogen receptor [ER] and progesterone receptor [PR]) and HER2 are not expressed, is reported to be the most diverse group." (PMID 37179317, 2023). "Here, we discuss the case of a patient with stage 4 estrogen receptor-positive, progesterone receptor-negative, human epidermal growth factor receptor 2-negative breast cancer who was on treatment with denosumab for bony metastases and presented with severe refractory hypocalcemia." (PMID 37404446, 2023). "PrP exposure could activate estrogen-related pathways, for example, 20 nM (3.6 μg/L) PrP stimulated both the mRNA (24 h exposure) and protein (48 h exposure) expression of the progesterone receptor (PGR), estrogen receptor ERα and Erβ in MCF-7 breast cancer cells." (PMID 36834249, 2023). "Triple negative breast cancer (TNBC) is a notoriously aggressive and highly metastatic classification of breast cancer characterized by a lack of expression of estrogen receptor (ER), progesterone receptor (PR), and human epidermal growth factor receptor 2 (HER2)." (PMID 36901842, 2023).
breast cancer (continued). "Hormone therapy still takes up a big share of the FDA-approved drugs for breast cancer therapy, and it is not surprising since the majority of the diagnosed breast cancers are estrogen receptor (ER) positive (~80%) or ER and progesterone receptor (PR) positive (~65%)." (PMID 37759706, 2023). "Triple-negative breast cancer (TNBC) is an aggressive form of breast cancer, which lacks the three receptors that are present in more common types of breast cancer; namely, the estrogen receptor, the progesterone receptor, and the human epidermal growth factor receptor type 2." (PMID 37422450, 2023). "However, about 33% of canine basal-like tumors are estrogen receptor negative (ER−) and progesterone receptor positive (PR+), which is rare in human breast cancer." (PMID 37034591, 2023). "TILs have a strong prognostic effect in the so-called triple-negative (oestrogen receptor, progesterone receptor, and human epidermal growth factor receptor-2 negative) subset of breast cancers and predict a better response when primary systemic (neoadjuvant) treatment is administered." (PMID 36831541, 2023). "Molecular breast cancer subtypes include normal-like (ER+, PGR+, HER2−, Ki67−), basal (ER−, PGR−, HER2−, basal marker+), luminal subtype A (LumA; ER+, PGR+, HER2−, Ki67−), luminal subtype B (LumB; ER+, PGR+, HER2−, Ki67+), HER2-positive (ER−, PGR−, HER2+), and triple-negative (ER−, PGR−, HER2−)." (PMID 37885013, 2023). "Breast cancer cell lines can be classified into four subtypes; luminal A, luminal B, HER2+ and triple negative (TN) based on the status of three hormonal receptors, namely estrogen receptor (ER), progesterone receptor (PR) and human epithelial receptor 2 (HER2)." (PMID 36675208, 2023). "Gallen expert consensus, i.e., luminal breast cancer expressing ERα and/or the progesterone receptor (PR), overexpressing (luminal B)—or not (luminal A/B)—the human epidermal growth factor receptor 2 (HER2) and/or having (luminal B)—or not (luminal A)—a high proliferative index (Ki-67)." (PMID 37190179, 2023). "Triple-negative breast cancer (TNBC) is a heterogeneous group of breast cancers defined by the absence of estrogen receptor (ER), progesterone receptor (PR), or human epidermal growth factor receptor 2 (HER2), and is minimally classified into 4 genomic subtypes." (PMID 37874652, 2023). "Progesterone receptor (PR)-negative tumors have been shown to have worse prognosis and were underrepresented in recent trials on patients with estrogen receptor (ER)-positive breast cancer." (PMID 37041481, 2023). "Triple-negative breast cancer (TNBC) is one of the most aggressive subtypes of breast cancer (BC) and is characterized by the lack of expression of the estrogen receptor (ER), the progesterone receptor (PR), and receptor 2 of the human epidermal growth factor (HER2)." (PMID 36980175, 2023). "Studies have shown that the luminal subtype of invasive breast cancer (oestrogen receptor and progesterone receptor-positive) has a significantly higher mast cell density compared to the non-luminal subtype of breast carcinoma (oestrogen receptor and progesterone receptor-negative)." (PMID 37928785, 2023). "Triple-negative breast cancer (TNBC) is an aggressive subtype of breast cancer which is negative for estrogen receptor (ER), progesterone receptor (PR), and human epidermal growth factor receptor 2 (HER2), which nullifies existing endocrine therapies and targeted therapies." (PMID 36042208, 2022). "In addition, CT-guided needle biopsy of the kidney and lung lesions was done and it was revealed that lesions of the left lung and the right kidney was breast cancer metastases (ER positive, PgR positive, HER2 negative)." (PMID 35038044, 2022). "Triple negative breast cancer (TNBC), a type of breast cancer with negative expression of estrogen receptor (ER), progesterone receptor (PR), and human epidermal growth factor receptor 2 (HER2), is characterized by rapid progress, metastasis, and invasion tendency." (PMID 36382024, 2022).
breast cancer (continued). "Triple negative breast cancer (TNBC) is a subtype of breast cancer (BC) defined by total lack of hormone receptor expression, i.e., estrogen receptor negative (ER−), progesterone receptor negative (PR−) and human epidermal growth factor receptor negative (Her2neu−)." (PMID 35377046, 2022). "Cancer immunotherapies have provided hope to patients with triple-negative breast cancer (TNBC) lung metastasis, an aggressive breast cancer expressing neither the estrogen receptor (ER), the progesterone receptor (PR), nor the human epidermal growth factor receptor 2 (HER2)." (PMID 35805039, 2022). "Triple-negative breast cancer (TNBC) is an aggressive subtype of breast cancer characterized by significant inter- and intra-tumor molecular heterogeneity and defined by the lack of expression of estrogen receptor (ER), progesterone receptor (PR), and HER2 receptor." (PMID 35076579, 2022). "Five intrinsic subtypes of breast cancer were initially identified: Luminal-A, Luminal-B, HER2+, triple negative/basal like (TNBC) and normal like, which is based on the gene expression of estrogen receptor (ER), progesterone receptor (PR), and human epidermal growth factor receptor 2 (HER2)." (PMID 35185887, 2022). "Triple-negative breast cancer (TNBC) represents 15–20% of all breast cancers, which is characterized by the lack of hormone receptors (HR), including estrogen receptor (ER) and progesterone receptor (PR) expression, in addition to the lack of epidermal growth factor receptor-2 (HER-2) amplification." (PMID 36142814, 2022). "Breast cancers are classified into four subtypes: Luminal A, Luminal B, HER2 (human epidermal growth factor receptor 2) overexpression and triple-negative (also known as basal-like), according to the expression of estrogen receptor (ER), progesterone receptor (PR), Ki-67 and HER-2." (PMID 35179718, 2022). "Triple-negative breast cancer (TNBC) is a subtype of breast cancer, which is a pathologically diverse disease of higher grade characterized by the absence of the estrogen receptor (ER), the progesterone receptor (PR), and the human epidermal growth factor receptor 2 (HER2) expressions." (PMID 35941873, 2022). "Conventionally, breast cancer can be classified according to the presence or absence of three biomarkers: estrogen receptor (ER), progesterone receptor (PR), and human epidermal growth factor receptor 2 (HER2), being called hormone receptor-positive or negative." (PMID 35892465, 2022). "Fourth, the HER2/estrogen/progesterone receptor status of the breast cancer patients was not retrieved from the NHIRD database for further adjustment and analysis, and these characteristics may have had confounding effects to the result." (PMID 36230488, 2022). "Approximately 60% of BRCA1-associated breast cancers are triple negative (TNBC), i.e., negative for estrogen receptor (ER), progesterone receptor (PR), and human epidermal growth factor receptor 2 (HER2); these are very aggressive and high-grade cancers with a poor prognosis." (PMID 35025764, 2022). "In particular, the triple-negative breast cancer (TNBC) subtype represents 10–12% of all breast cancers and is defined by the lack of estrogen receptor (ER), progesterone receptor (PR) expression, and human epidermal growth factor receptor 2 ((HER2) amplification." (PMID 34370182, 2022). "ER– breast cancers are more aggressive than ER+ breast cancers, and TNBCs are the most aggressive sub-type and also very difficult to treat due to their lack of ER, progesterone receptor and HER2 expression." (PMID 34497382, 2022). "Further, we were not able to evaluate SMRs by breast cancer subtype (estrogen receptor, progesterone receptor, and human epidermal growth factor receptor 2 status) or by hormone therapy use since these data were not available consistently throughout our follow-up." (PMID 35107712, 2022).